MUC1 (mucin 1, cell surface associated)
Diseases named in the same sentence as MUC1 in open-access papers (continued):
Sharing a sentence is not in itself a finding about the gene and the disease.
breast carcinoma (continued). "Interestingly, we detected almost no binding of SM3GRNLY to the lung tumor A549 or to the mammary tumor MCF7, although it has been suggested that these cell lines express the MUC-1 Tn antigen." (PMID 32859066, 2020). "The reason why CA15-3 can predict the prognosis in breast cancer is not fully clear, but as CA15-3 is the soluble form of MUC1, this may be related with the function of MUC1." (PMID 29854028, 2018). "Vaccines containing per-glycosylated MUC1 antigens, when injected in PBS without external adjuvant or formulation into liposomes, induced high titers of MUC1 antibodies capable of recognizing MCF-7 breast cancer cells." (PMID 26557640, 2015). "These constructs were able to induce MUC1-specific, class-switched antibodies in the absence of a canonical adjuvant, and were capable of inducing complement-dependent lysis of MCF-7 breast cancer cells, while T cell responses to the vaccines were not reported." (PMID 26557640, 2015). "Using these criteria, all 30 healthy individuals tested were found to be negative, while in the group of early breast cancer patients, CTC were detected in 42/254 patients (16.5%) with the positive expression rates of 3.5% for GA733-2, 5.5% for MUC-1 and 10.2% for HER-2." (PMID 23497487, 2013). "In addition, both parental bipotent and MPCs do not express proteins such as, claudin 3, ER, ESA, MUC1 and GATA3, that are known signature of claudin-low breast cancers." (PMID 22514728, 2012). "A total of 22 WT mice were used, of which 16 received lung tissue cells from MMT mice, three WT mice received lung tissue cells collected from MUC1.Tg mice as negative controls, and three WT mice were injected with CD44+ tumor cells sorted from primary MMT mammary tumors, as positive controls." (PMID 22277639, 2012). "MAL2/MUC1 interactions were detected in Triton X-100-soluble membrane fractions, indicating that MAL2 has specific functions within non-raft membrane compartments in breast cancer cells." (PMID 19175940, 2009).
pancreatic cancer (265 papers, 2003 to 2026). "Bioinformatic analysis revealed that MUC1 was highly expressed in pancreatic cancer tissues and associated with poor patient prognosis." (PMID 41607777, 2026). "This study seeks to establish a novel immunotherapeutic strategy for pancreatic cancer and to elucidate the mechanisms underlying the intervention of DC vaccines loaded with MUC1 peptides." (PMID 41607777, 2026). "Further analysis revealed that high expression of MUC1 was associated with significantly reduction of overall survival in pancreatic cancer patients (P < 0.05)." (PMID 41607777, 2026). "Mucin 1 (MUC1) was another tumor-associated antigen presented in pancreatic cancer cells, considering a promising antigen for immunotherapy." (PMID 41190066, 2025). "For example, MUC4, which belongs to the same family as MUC1, is recognized as a biomarker for cancer metastasis in pancreatic and colorectal cancers, and is also associated with prognosis in pancreatic cancer." (PMID 40909948, 2025). "On the other hand, abnormal MUC1 expression is linked to tumor resistance to chemotherapy and a grim prognosis in pancreatic cancer." (PMID 40699746, 2025). "The cancer stem cell (CSC) phenotype is known to be involved in mediating the resistance to chemotherapy, and MUC1 has been associated with the self renewal and maintenance of CSCs in breast and pancreatic cancers." (PMID 38254882, 2024). "MUC1, a transmembrane mucin glycoprotein, has been linked to the most aggressive types of pancreatic cancer." (PMID 39201656, 2024). "According to a prior study, aberrant MUC1 overexpression is seen in over 60% of pancreatic cancers, and this finding is associated with a bad prognosis for the patients." (PMID 38540735, 2024). "On the other hand, threonine deficiency and tRNA synthetase inhibition can reduce MUC1 levels in pancreatic cancer cells, thereby inhibiting tumor cell migration." (PMID 38361923, 2024). "Pancreatic cancers are known to be resistant to these treatments, and the overexpression of MUC1, a member of the glycoprotein mucins, is associated with IR- and chemo-resistance." (PMID 38927743, 2024). "While the genetics the Pan02 cells remain to be fully elucidated, Pan02 (also known as Panc02) cells are reported to carry many common mutations in human pancreatic cancers, including Muc1 and Muc4." (PMID 38547077, 2024). "During PNI in pancreatic cancer, cancer cells that overexpress membrane-bound mucin 1 (MUC1) can establish strong adhesion with myelin-associated glycoprotein (MAG) on Schwann cells." (PMID 39061654, 2024). "Paradoxically, our study did not seem to confirm this correlation though many studies suggested that MUC1 was associated with pancreatic cancer progression." (PMID 35709153, 2022). "As a cancer associated protein, MUC1 has also been used as a biomarker for the diagnosis of pancreatic cancer." (PMID 35197099, 2022). "Our results indicate that HzMUC1-MMAE not only causes cell G2/M cycle arrest but also induces apoptosis of MUC1 positive pancreatic cancer cells." (PMID 36572921, 2022). "For instance, MUC1 is a glycoprotein almost exclusively expressed by high-risk pancreatic cysts as well as in cells of pancreatic cancer itself." (PMID 35410389, 2022). "MUC1 is highly expressed in pancreatic cancer and it was associated with invasion, metastasis, and unfavorable overall survival, and inducing epithelial-mesenchymal transition." (PMID 33921242, 2021). "Low MUC1 expression is significantly associated with favorable prognosis in patients with pancreatic cancer after curatively intended resection." (PMID 34386419, 2021). "An association of MUC1 upregulation and gemcitabine resistance in pancreatic tumor cells was described in several preclinical investigations." (PMID 34386419, 2021).
pancreatic cancer (continued). "One such approach that has been tested in the context of pancreatic cancer is the adoptive transfer of T cells specific for MUC1, a tumour-associated antigen overexpressed in invasive ductal carcinomas of the pancreas." (PMID 33920118, 2021). "TAB004 was also shown to be a diagnostic marker for cancer stem cells and circulating MUC1 in mice and patients with pancreatic cancer." (PMID 33167508, 2020). "An intriguing and novel finding of MUC1 deficiency under physiological conditions is the inhibition of the SPINK pancreatic cancer pathway." (PMID 32793510, 2020). "MUC1 overexpression specifically has been linked to tumor progression, invasion and metastasis in breast and pancreatic cancer cells." (PMID 29987260, 2018). "Pancreatic cancer cells express high levels of MUC1, MUC4 and MUC16 mRNAs that encode membrane-bound mucins." (PMID 28262838, 2017). "More recently, CAR that recognized cancer-associated Tn-glycoform of MUC-1 has been developed, with target-specific cytotoxicity and tumor growth control in xenograft models of T cell leukemia and pancreatic cancer." (PMID 28399903, 2017). "In pancreatic cancer, the presence of MUC1 IgG autoantibodies has been associated with a favorable prognosis." (PMID 27659305, 2016). "MUC-1 is overexpressed in pancreatic cancers and has been shown to associate with HIF-1 alpha to drive the expression of hypoxia-induced oncogenes, including PDGF, whose receptors, PDGFRalpha and PDGFRbeta regulate PDCA cell migration and metastasis." (PMID 26808546, 2016). "This is the first report that clearly suggests a functional role of pancreatic tumor-associated MUC1 in the development of functional MDSCs." (PMID 24605110, 2014). "Overexpression of MUC1 has been associated with potential risk of metastasis of colon cancer, pancreatic cancer and oral squamous cell carcinoma." (PMID 24176033, 2013). "In an attempt to understand the molecular mechanism of cell survival and the role of HSP70 and MUC1 in pancreatic cancer cells, we looked into the association of HSP70 and MUC1." (PMID 22912777, 2012). "In pancreatic cancer this is associated with PDGF induced phosphorylation of MUC1 a transmembrane glycoprotein involved in pancreatic tumor progression and metastasis." (PMID 21781317, 2011). "Circulating antibodies to MUC1 are associated with a favorable prognosis in pancreatic cancer, while expression of MUC1 indicates a poor prognosis in pancreatobiliary pancreatic head tumors." (PMID 22027009, 2011). "STn and Tn on MUC1 expressed on tumor cells contribute to perineural invasion in pancreatic cancer by binding to myelin-associated glycoprotein (MAG), a member of the Siglec family of sialic acid-binding lectins expressed on oligodendrocytes and Schwann cells." (PMID 24212946, 2011). "Over-expression of Muc-1 is often associated with colon, breast, ovarian, lung and pancreatic cancers." (PMID 22152097, 2011). "HLA-unrestricted CTL from ovarian, breast and pancreatic carcinoma patients also have been reported and they are known to recognize epitopes of mucin (MUC1) tumor-associated antigen." (PMID 16281981, 2005). "In the study of mucin expression in mouse models, MUC1 overexpression was associated with the metastasis of pancreatic adenocarcinoma to the lung, liver, and peritoneal organs, as well as increased multidrug resistance in pancreatic cancer cells." (PMID 40699805, 2025). "However, in studies of pancreatic cancer, high MUC1 expression has been strongly associated with the invasiveness of pancreatic cancer." (PMID 40699805, 2025). "Recent studies in pancreatic cancer treatment demonstrate that targeting tumor-associated MUC1 (tMUC1) with the monoclonal antibody TAB004 overcomes anoikis resistance by specifically binding to tMUC1, reducing cancer cell viability and promoting its degradation." (PMID 38361923, 2024).
pancreatic cancer (continued). "Other putative STAT3 targets were DPYD, a gene encoding a key 5-FU-metabolizing enzyme, MUC1, which impacts on the response to radiotherapy in pancreatic cancer, and HIF1A, an established target of JAK-STAT signaling and previously reported as potential determinant of tumor radiosensitivity." (PMID 33530306, 2021). "GP1.4 is an anti-MUC1 antibody that caused internalization of EGFR in pancreatic cancer cells." (PMID 33167508, 2020). "The Muc-1 oncoprotein is a tumor-associated mucin often overexpressed in pancreatic cancer." (PMID 31337812, 2019). "For example, MUC1 encodes glycoprotein Mucin 1 with extensive O-linked glycosylation of its extracellular domain and overexpression of MUC1 is often associated with colon, breast, ovarian, lung and pancreatic cancers." (PMID 28245581, 2017). "Further, inhibition of this association by inhibition of either HSP70 expression or MUC1 activity could be of significant therapeutic value in pancreatic cancer." (PMID 22912777, 2012). "To see whether MUC1-c is associated with HSP70 in pancreatic cancer cells, we tested for co-precipitation of MUC1 and HSP70 in pancreatic cancer cells." (PMID 22912777, 2012). "The human tumor antigen mucin, encoded by the gene MUC1, is a high-molecular-weight glycoprotein that is overexpressed in adenocarcinomas including pancreatic cancer and hematological cancers and can be recognized by cytotoxic T lymphocytes (CTLs) and monoclonal antibodies." (PMID 21922022, 2011). "One explanation is that after binding the surface MUC1 antigen, 213Bi-C595 may form 213Bi-C595–MUC1 complexes at the cell membrane, emitting α particles that kill pancreatic cancer cells by causing double-DNA-strand breaks." (PMID 15599383, 2004). "In addition, high MUC-1 expression is associated with poor prognosis in pancreatic cancer." (PMID 38756774, 2024). "Therefore we suggest that ELISA measurements of serum HIP/HAP and MUC-1 levels could be added to a panel of tests for the routine screening of population to identify individuals at increased risk for the developing pancreatic carcinoma." (PMID 19956730, 2009). "The cytotoxic activity of CTLs induced respectively by PBS, antigen-unloaded DC, and MUC1 antigen peptides 568 and 619 loaded DC were evaluated against pancreatic cancer cell lines PANC-1, BXPC-3, and MIA PaCa-2." (PMID 41607777, 2026). "In conclusion, this study highlights the therapeutic potential of MUC1 peptide-loaded DC vaccines in pancreatic cancer." (PMID 41607777, 2026). "The results showed that MUC1 was significantly overexpressed in pancreatic cancer tissues (P < 0.0001)." (PMID 41607777, 2026). "Bioinformatics analysis was performed to evaluate the differential expression of MUC1 in pancreatic cancer patients compared to normal tissues." (PMID 41607777, 2026). "The results demonstrated that CTLs activated by DC vaccines loaded with MUC1 antigen peptides exhibited potent cytotoxic activity against all three pancreatic cancer cell lines, with increasing cytotoxicity in a dose-dependent manner." (PMID 41607777, 2026). "This study aimed to evaluate the efficacy of a dendritic cell (DC) vaccine pulsed with mucin 1 (MUC1) peptide antigens in the immunotherapy of pancreatic cancer." (PMID 41607777, 2026). "The results demonstrated that HzMUC1-MMAE effectively bound to MUC1 on the surface of pancreatic cancer cells, significantly inhibiting their growth by inducing G2/M cell cycle arrest and apoptosis." (PMID 40699746, 2025). "In pancreatic cancer cells, MUC1 expression increases in a time-dependent manner under hypoxic conditions." (PMID 40001578, 2025). "In another phase I study, patients with resected or locally advanced pancreatic cancer were given a synthetic MUC1 peptide vaccine with SB-AS2 adjuvant, followed by adjuvant therapy at the physician’s discretion." (PMID 40723238, 2025).
pancreatic cancer (continued). "Among cancer hallmarks, glucose metabolism is also altered; for example, in Network 1, the Mucin1 gene (MUC1) are overexpressed in several carcinomas and are related to the hypoxic response in pancreatic cancer cells." (PMID 40013338, 2025). "In treating pancreatic cancer, mAb and TAB004, which target tumors associated with MUC1 (tMUC1), have shown a reduction in colony formation in the PDAC cell line." (PMID 40699805, 2025). "In another phase I trial, DCs were isolated from the peripheral blood of patients with advanced pancreatic cancer and pulsed with a MUC-1 peptide." (PMID 40723238, 2025). "Experimental data, such as from pancreatic cancer models, are needed to clarify MUC1's exact role in CRC." (PMID 41332218, 2025). "Mucin 1 (MUC1), a transmembrane glycoprotein, is aberrantly glycosylated and frequently overexpressed in pancreatic cancer." (PMID 40001578, 2025). "MUC1 was used as a target for the treatment of epithelial ovarian tumour in the included trial and for pancreatic tumour in another trial, but this trial was terminated prematurely without a positive outcome for RIT." (PMID 40361339, 2025). "The 213Bi-C595 conjugate demonstrated specific cytotoxicity to MUC1-positive pancreatic cancer cells in a concentration-dependent manner, inducing apoptosis and reducing cell viability significantly compared to controls." (PMID 40699746, 2025). "Tumor-associated mucins, including Mucin-1 (MUC1), have long been studied as potential TAAs in pancreatic cancer and other epithelial tumors." (PMID 40723238, 2025). "In summary, the present review emphasizes the roles of some microRNAs, GATA6, L1CAM, and MUC1 in pancreatic cancer." (PMID 40699746, 2025). "Tn-MUC1, a truncated form of MUC1 decorated with Tn antigen, is frequently overexpressed in pancreatic cancer." (PMID 41372740, 2025). "Some experiments on mouse model and a few clinical trials on pancreatic cancer and other solid tumors demonstrated that DCs vaccines loaded with MUC1 show an effective durable response with good safe and tolerability." (PMID 40001578, 2025). "MUC1 DNA vaccines also exhibited potent anti-tumor effects on pancreatic cancer experimental models, which await further investigation in the clinical setting." (PMID 41190066, 2025). "This review aims to discuss the new functions of important biomarkers, such as miRNAs, GATA6, L1CAM, and MUC1 in pancreatic cancer." (PMID 40699746, 2025). "The numerous clinical trials activated in the last ten years demonstrate how the preparation of anti-tumor drugs against MUC1 is of great importance for the comprehensive treatment of pancreatic cancer." (PMID 40001578, 2025). "CARs targeting MUC1 glycoforms containing short O-glycan structures have demonstrated promising preclinical efficacy in leukemia and pancreatic cancer models." (PMID 40925376, 2025). "For example, Decitabine, a DNA methylation transferase inhibitor, can enhance the specific recognition and killing effect of MUC1 CAR-T by upregulating the expression of MUC1 antigen on pancreatic cancer cells." (PMID 38911868, 2024). "In this study, we investigated the role of MUC1, a mucin protein overexpressed in pancreatic cancer, in regulating polyamine metabolism." (PMID 38547055, 2024). "Consistent with the reported oncogenic role of MUC1, we observed a significant reduction in the growth of the pancreatic cancer cells in 3D-spheroid assays." (PMID 38547055, 2024). "Taken together, our data identified MUC1 as a key regulator of polyamine metabolite levels in pancreatic cancer cells through SAT1 enzyme." (PMID 38547055, 2024). "MUC1 is a membrane-bound glycoprotein that is aberrantly glycosylated, localized, and expressed in many cancers, including pancreatic cancer." (PMID 38547055, 2024). "We have previously demonstrated that MUC1-mediated stabilization of HIF-1α is critical for metabolic reprogramming in pancreatic cancer cells." (PMID 38547055, 2024).